ENSG00000267748 (novel protein)
Gene: Protein-coding gene on chromosome 19 (38,289,151 to 38,304,910, forward strand). Ensembl gene ENSG00000267748.
Genetic constraint (gnomAD): Loss-of-function variants: 12 observed, 16.5 expected, observed/expected ratio (o/e) 0.73, 90% interval 0.47 to 1.18. Missense variants: 207 observed, 214.7 expected, observed/expected ratio (o/e) 0.96, 90% interval 0.86 to 1.08. Synonymous variants: 67 observed, 76.99 expected, observed/expected ratio (o/e) 0.87, 90% interval 0.71 to 1.07.